UTP25 (UTP25 small subunit processome component)
Description:
Component of the ribosomal small subunit processome for the biogenesis of ribosomes, functions in pre-ribosomal RNA (pre-rRNA) processing (By similarity). Controls the expansion growth of digestive organs and liver. Also involved in the sympathetic neuronal development (By similarity).
Synonyms: C1orf107; DEF; DIEXF; MGC29875; DJ434O14.5
Tractability: PROTAC: ubiquitination databases record sites on it.
Gene: Protein-coding gene on chromosome 1 (209,827,972 to 209,857,565, forward strand). Ensembl gene ENSG00000117597.
Subcellular location: Nucleus, nucleolus
Pathways (Reactome):
Metabolism of RNA: Major pathway of rRNA processing in the nucleolus and cytosol; rRNA modification in the nucleus and cytosol
Gene Ontology:
Molecular function: protein binding; RNA binding; rRNA binding; U3 snoRNA binding
Biological process: embryonic organ development; protein catabolic process; protein destabilization; protein localization to nucleolus; maturation of SSU-rRNA from tricistronic rRNA transcript (SSU-rRNA, 5.8S rRNA, LSU-rRNA); positive regulation of embryonic development; rRNA processing
Cellular component: nucleolus; nucleoplasm; small-subunit processome
Genetic constraint (gnomAD): Loss-of-function variants: 49 observed, 81.85 expected, observed/expected ratio (o/e) 0.6, 90% interval 0.47 to 0.76. The upper end of that interval is the gene's LOEUF score, 0.76, which puts it in group 3 of 6, group 1 being the genes least tolerant of losing a copy. Missense variants: 846 observed, 959.57 expected, observed/expected ratio (o/e) 0.88, 90% interval 0.83 to 0.93. Synonymous variants: 329 observed, 356.58 expected, observed/expected ratio (o/e) 0.92, 90% interval 0.84 to 1.01.
Homologues: Orthologues: chimpanzee UTP25 (99% identical), macaque UTP25 (98% identical), rabbit UTP25 (92% identical), pig UTP25 (90% identical), dog UTP25 (90% identical), rat Utp25 (88% identical), mouse Utp25 (88% identical), guinea pig UTP25 (79% identical), tropical clawed frog utp25 (68% identical), zebrafish utp25 (54% identical), Drosophila melanogaster CG3735 (33% identical), Caenorhabditis elegans Y41C4A.9 (24% identical).
Diseases named in the same sentence as UTP25 in open-access papers:
UTP25 is named in the same sentence as 10 diseases in open-access papers, as found by Europe PMC text mining. Sharing a sentence is not in itself a finding about the gene and the disease. The quoted sentences say what the papers report.
cleft lip (1 paper, 2025). Congenital defect in the upper lip where the maxillary prominence fails to merge with the merged medial nasal prominences. "However, three SNPs showed some weak evidence of an effect on PRS in the opposite direction to their effect on cleft lip phenotypes: rs62390705 (FBN2, 5q23.3) (P = 0.05), rs126280 (UTP25, 1q32.2) (P = 0.002), and rs4952552 (PKDCC, 2q14.2) (P = 0.04)." (PMID 41075272, 2025).
gastric cancer (1 paper, 2023). A primary or metastatic malignant neoplasm involving the stomach. "When the eight characteristic genes (ENTPD3, PDZD4, CNN1, GTPBP4, FPGS, UTP25, CENPW, and FAM111A) are all fitted into one variable, the AUC of the ROC curve is 0.996, indicating a good diagnostic efficiency for gastric cancer." (PMID 37007099, 2023). "We have established the early diagnosis model of eight characteristic genes (ENTPD3, PDZD4, CNN1, GTPBP4, FPGS, UTP25, CENPW, and FAM111A) for gastric cancer." (PMID 37007099, 2023).
neuroblastoma (1 paper, 2019). Neuroblastoma (NB) is the most common solid, extracranial childhood tumor. "Similarly, in the context of N-MYC-driven neuroblastomas, MYC oncogene was shown to control the transcription of the DEF/UTP25 gene, whose encoded protein participates in the proper processing of 18S rRNA species." (PMID 31533350, 2019). "As a result, UTP25 synergizes with N-MYC to foster tumor development both in Zebrafish and in human cells, while its haploinsufficiency reduces the growth of N-MYC-driven neuroblastoma cells." (PMID 31533350, 2019).
cancer (1 paper, 2025). A tumor composed of atypical neoplastic, often pleomorphic cells that invade other tissues. "These genes include SERTAD4, IRF6, TRAF3IP3, and UTP25, which are involved in embryo development, cancer, innate immune response, and epigenetic processes." (PMID 40007031, 2025).
UTP25 also shares sentences with these, for which no sentence is quoted: tumor (3 papers); Anxiety (1); colon cancer (1); leukemia (1); nicotine dependence (1); pancreatic cancer (1).